CD74 (CD74 molecule)
Description:
Plays a critical role in MHC class II antigen processing by stabilizing peptide-free class II alpha/beta heterodimers in a complex soon after their synthesis and directing transport of the complex from the endoplasmic reticulum to the endosomal/lysosomal system where the antigen processing and binding of antigenic peptides to MHC class II takes place. Serves as cell surface receptor for the cytokine MIF. [Class-II-associated invariant chain peptide]: Binds to the peptide-binding site of MHC class II alpha/beta heterodimers forming an alpha-beta-CLIP complex, thereby preventing the loading of antigenic peptides to the MHC class II complex until its release by HLA-DM in the endosome. [Isoform p41]: Stabilizes the conformation of mature CTSL by binding to its active site and serving as a chaperone to help maintain a pool of mature enzyme in endocytic compartments and extracellular space of antigen-presenting cells (APCs). Has antiviral activity by stymieing the endosomal entry of Ebola virus and coronaviruses, including SARS-CoV-2. Disrupts cathepsin-mediated Ebola virus glycoprotein processing, which prevents viral fusion and entry. This antiviral activity is specific to p41 isoform.
Synonyms: Ii; CLIP; DHLAG; HLADG; Ia-GAMMA; p33
Tractability: Small molecule: an approved drug acts on it; a high-quality ligand is known; it has a high-quality binding pocket. Antibody: a drug acting on it is in phase 2 or 3 trials; UniProt places it where antibodies can reach, with high confidence; its Gene Ontology location is reachable by antibodies, with high confidence; UniProt predicts a signal peptide or a membrane-spanning region. PROTAC: ubiquitination databases record sites on it; its protein half-life has been measured; a small molecule that binds it is known.
Target class: Surface antigen
Gene: Protein-coding gene on chromosome 5 (150,401,637 to 150,412,969, reverse strand). Ensembl gene ENSG00000019582.
Subcellular location: Cell membrane; Endoplasmic reticulum membrane; Golgi apparatus, trans-Golgi network; Endosome; Lysosome; Secreted; Late endosome (Isoform p41)
Subcellular location (Human Protein Atlas): Golgi apparatus; Predicted to be secreted
Pathways (Reactome):
Developmental Biology: Developmental Lineage of Pancreatic Ductal Cells
Hemostasis: Cell surface interactions at the vascular wall
Immune System: MHC class II antigen presentation
Gene Ontology:
Molecular function: amyloid-beta binding; CD4 receptor binding; cytokine binding; cytokine receptor activity; macrophage migration inhibitory factor binding; MHC class II protein binding, via antigen binding groove; MHC class II protein complex binding; protein binding; protein folding chaperone; identical protein binding; MHC class II protein binding; nitric-oxide synthase binding
Biological process: negative regulation of apoptotic process; negative regulation of cell migration; negative regulation of peptide secretion; positive regulation of B cell proliferation; positive regulation of canonical NF-kappaB signal transduction; positive regulation of chemokine production; positive regulation of cytokine-mediated signaling pathway; positive regulation of ERK1 and ERK2 cascade; positive regulation of fibroblast proliferation; positive regulation of gene expression; positive regulation of interleukin-6 production; positive regulation of interleukin-8 production; positive regulation of macrophage migration inhibitory factor signaling pathway; positive regulation of monocyte differentiation; positive regulation of prostaglandin biosynthetic process; prostaglandin biosynthetic process; response to type II interferon; antigen processing and presentation; antigen processing and presentation of endogenous antigen; immunoglobulin mediated immune response; intracellular protein transport; positive regulation of chemokine (C-X-C motif) ligand 2 production; positive regulation of macrophage cytokine production; and 13 more
Cellular component: cell surface; cytoplasm; extracellular exosome; extracellular region; Golgi apparatus; macrophage migration inhibitory factor receptor complex; membrane; nucleus; plasma membrane; protein-containing complex; vacuole; clathrin-coated endocytic vesicle membrane; endocytic vesicle membrane; ER to Golgi transport vesicle membrane; Golgi membrane; late endosome; lumenal side of endoplasmic reticulum membrane; lysosomal lumen; lysosomal membrane; lysosome; MHC class II protein complex; trans-Golgi network membrane; transport vesicle membrane; endoplasmic reticulum; endoplasmic reticulum membrane; and 4 more
Genetic constraint (gnomAD): Loss-of-function variants: 18 observed, 31.42 expected, observed/expected ratio (o/e) 0.57, 90% interval 0.4 to 0.85. The upper end of that interval is the gene's LOEUF score, 0.85, which puts it in group 3 of 6, group 1 being the genes least tolerant of losing a copy. Missense variants: 321 observed, 371.14 expected, observed/expected ratio (o/e) 0.86, 90% interval 0.79 to 0.95. Synonymous variants: 143 observed, 147.12 expected, observed/expected ratio (o/e) 0.97, 90% interval 0.85 to 1.12.
Homologues: Orthologues: chimpanzee CD74 (99% identical), macaque CD74 (94% identical), guinea pig CD74 (78% identical), dog CD74 (75% identical), pig CD74 (75% identical), rat Cd74 (73% identical), mouse Cd74 (73% identical), rabbit CD74 (72% identical), tropical clawed frog cd74 (29% identical), zebrafish cd74a (23% identical), zebrafish cd74b (17% identical).
Diseases named in the same sentence as CD74 in open-access papers:
CD74 is named in the same sentence as 323 diseases in open-access papers, as found by Europe PMC text mining. Sharing a sentence is not in itself a finding about the gene and the disease. The quoted sentences say what the papers report.
melanoma (65 papers, 2010 to 2026). A malignant, usually aggressive tumor composed of atypical, neoplastic melanocytes. "In one study, CD74 was found to be a favorable prognostic marker associated with enhanced immune infiltration and improved survival in patients with stage IV melanoma." (PMID 41597203, 2026). "As CD74 is found primarily on immune subsets where it is associated with improved outcomes in melanoma, we evaluated the ratio of CD74 to its ligands MIF and DDT." (PMID 39028303, 2024). "Our analysis of two independent cohorts, which are one for protein in TMA and one for their genes in TCGA, implicated that increased CD74 expression is a marker of good prognosis in stage IV melanoma." (PMID 33327409, 2020). "Our data demonstrates CD74 as a useful prognostic tumor cell protein marker associated with favorable OS in stage IV melanoma as we have previously shown in stage III melanomas." (PMID 33327409, 2020). "Our data here presents CD74 as a prognostic tumor marker associated with good survival in stage IV melanoma." (PMID 33327409, 2020). "In conclusion, our data demonstrates CD74 as a useful prognostic tumor cell protein marker associated with favorable OS in stage IV melanoma as we have previously shown in stage III melanomas." (PMID 33327409, 2020). "Our data validates CD74 as a useful prognostic tumor cell protein marker associated with favorable OS as in stage III melanomas, while the tumor NT expression strongly predicts an increased risk of developing CNS metastasis (p = 0.0008) in those patients." (PMID 33327409, 2020). "In the total cohort of BM as well as in the subcohort of melanoma BM the positive prognostic marker CD74 on tumor cells is nevertheless significantly associated with increased numbers of TILs (including CD3-, CD4- and CD8-positive TILs)." (PMID 29490700, 2018). "Progression of melanoma and other malignant cancers involves cellular changes such as the loss of E-cadherin expression and the gain of CD74 expression, which confer cell motility and immunologic escape, respectively." (PMID 20338038, 2010). "As biomarkers, MIF and CD74 were identified as key proteins associated with melanoma prognosis." (PMID 41159021, 2025). "In addition, overexpressed CD74 was reported to interplay with MIF to promote the tumor growth in advanced melanoma patients, and its elevated expression was associated with the poorer patient survival." (PMID 38874510, 2024). "Specifically, CD74 expression was positively associated with immune infiltration in advanced solid tumor microenvironment, consistent with previous studies in patients with glioma, hepatocellular carcinoma, melanoma, and malignant pleural mesothelioma." (PMID 38280003, 2024). "Expression of CD74 associated with favorable survival for stage III melanoma." (PMID 35603163, 2022). "In our current study, we tested our hypothesis on CD74-regulated inflammatory markers’ expression in stage IV melanoma tumors whether the signature is associated with survival outcome and/or risk of developing CNS metastasis." (PMID 33327409, 2020). "Indeed, CD74 expression is associated with melanoma progression but, as previously seen (Section 2.1), high levels of CD74 in melanoma metastasis are associated with a better overall and recurrence-free survival, in the absence of MIF in the tumor microenvironment." (PMID 31013837, 2019). "sCD74, mainly the 25-kDa form derived from 33 kDa CD74 isoform, is secreted by melanoma cells and macrophages and is enhanced by IFN-γ." (PMID 41597203, 2026). "In contrast, high tumor CD74 expression was the strongest favorable prognostic marker among several inflammatory proteins examined in advanced melanoma in other studies." (PMID 41597203, 2026). "CD74′s prognostic value varies by tumor type: favorable in immune-inflamed cancers such as melanoma and HCC, but adverse in malignancies driven by MIF-mediated survival signals such as lymphomas and PDAC." (PMID 41597203, 2026).
melanoma (continued). "Activation of CD74 by MIF contributes to melanoma progression, as presented by its influence on immune responses like TNF-α signaling and apoptosis in the TME." (PMID 41159021, 2025). "For sCD74, it has been shown that sCD74 levels have a prognostic role in melanoma, correlating with tumor tissue CD74 expression." (PMID 39910579, 2025). "We and others have noted a direct correlation between immune infiltration, melanoma responses, and intratumor CD74 levels." (PMID 41122966, 2025). "This analysis also does not factor in epigenetic regulators of MIF expression or expression of the MIF homolog DDT (or MIF-2), which also engages the cognate MIF receptor CD74 and is expressed in many tumor types, including melanoma." (PMID 41122966, 2025). "A previous study showed that enhanced CD74/MIF interactions activated the PI3K/AKT pathway in melanoma and resulted in the promotion of tumor survival." (PMID 38256356, 2024). "Genetic, transcriptomic, and proteomic analyses of DDT, CD74:MIF, and CD74:DDT in patients with melanoma can further shed light on the differential expression among varying disease stages, tumor subtypes, mutational statuses, and ICI use." (PMID 39028303, 2024). "Currently, targeting the MIF/CD74 axis is a promising strategy for treating and overcoming resistance to immune checkpoint blockade therapy in melanoma and modulating the TME to promote effective antitumor immunity." (PMID 39028303, 2024). "Many studies have investigated CD74 as a biomarker of ICB response in melanoma; additionally, it shows promise for other cancers, including triple-negative breast cancer, although there is a paucity of studies exploring its utility in these cases." (PMID 38730725, 2024). "Another CDR cyclic peptide formulation (Rb9) also exhibited immunomodulatory effects on DCs by disturbing MIF/CD74 axis, boosting melanoma immunogenicity, when treating advanced lung metastasis." (PMID 37454231, 2023). "Our present work suggests that sCD74 displayed moderate antiproliferative capacity, by acting as a “decoy” receptor for MIF, and was antagonistic to the MIF/CD74/AKT-survival signaling pathway in melanoma." (PMID 35121729, 2022). "We sought the possible cellular sources of sCD74 in melanoma based on the theoretical assumption that sCD74 is released from CD74-expressing cells." (PMID 35121729, 2022). "Our findings point to CD74 as an intriguing molecule possessing multifaceted functions in melanoma, some contradictory, depending on the context." (PMID 35121729, 2022). "We chose melanoma cells and immune cells as potential candidates since CD74 is expressed in both tumor tissue and tumor microenvironment." (PMID 35121729, 2022). "To identify CD74 isoforms responsible for the generation of sCD74, we established A375 and SK-MEL-2 melanoma cells stably overexpressing the p33 and p35 isoforms of CD74, which are the main isoforms of CD74 in these cells." (PMID 35121729, 2022). "Conversely, we have recently demonstrated that high expression of CD74 in the tumors showed the most promise, among a set of inflammatory protein markers tested, as a favorable survival predictor in advanced melanoma." (PMID 35121729, 2022). "Apart from melanoma, CD74 and MIF have been considered as therapeutic targets in other cancer types such as prostate cancer and gastric cancer." (PMID 35769782, 2022). "Overall, our findings provide potential clinical benefit by using CD74 in combination with active novel therapies in melanoma, including targeted therapies and/or immunotherapies." (PMID 33327409, 2020). "As a result, the expression of CD74 and the loss of MIF only showed a favorable overall survival in stage IV melanoma patients (p = 0.0264)." (PMID 33327409, 2020). "To identify genes that are under- or over-expressed in samples with low or high CD74 expression in stage IV melanoma, we compared the expression of genes in the CD74 low (below median) and CD74 high (above median) sample groups." (PMID 33327409, 2020).
melanoma (continued). "We have previously observed weakened outcomes in patients with constitutive expression of inducible nitric oxide synthase (iNOS), macrophage migration inhibitory factor (MIF) and improved outcomes with CD74 expression in stage III melanoma." (PMID 33327409, 2020). "We have also previously reported compromised outcomes in patients with constitutive expression of inducible nitric oxide synthase (iNOS), macrophage migration inhibitory factor (MIF) and better outcomes with CD74 expression in stage III melanoma." (PMID 33327409, 2020). "The Cox regression analysis also indicated CD74 as one of the higher-ranking genes positively correlated to overall survival in patients with melanoma." (PMID 31212865, 2019). "Another, previously studied, CDR peptide (C36L1) showed ability to bind to MIF's receptor CD74 and also interfere in the melanoma-secreted factor that regulates macrophage function." (PMID 32010152, 2019). "In patients, it has been observed that IFN-γ levels in plasma correlated with CD74 expression in melanoma tissues." (PMID 31013837, 2019). "This regulation has been demonstrated in vitro by an increased transcription and cell surface expression of CD74 in melanoma cell lines following IFN-γ stimulation." (PMID 31013837, 2019). "Intriguingly, in melanomas, the expression of CD74, the main receptor of MIF, correlated with a favorable patient outcome." (PMID 31013837, 2019). "We analyzed the effects of a siRNA mediated CD74 knockdown on HLA-expression and HLA peptidome composition in a brain metastatic melanoma cell line." (PMID 29490700, 2018). "CD74 expression appeared to be restricted to intracellular compartments of H1 brain seeking melanoma cells." (PMID 29490700, 2018). "CD74 itself is upregulated in a variety of peripheral (e.g. melanoma:, lung cancer:) and especially hematopoietic neoplasms." (PMID 29490700, 2018). "Several studies have reported that CD74 is expressed on both the cell surface and intra-cellularly in B cell lymphoma, T cell lymphoma, melanoma cells and gastric epithelial cells." (PMID 25647395, 2015). "IFN-γ promotes ultraviolet-mediated melanomagenesis and melanoma cell survival by regulating CD74-macrophage-migration inhibitory factor (MIF) signaling, leading to the activation of AKT phosphorylation and the expression of IL-6, IL-8, and B-cell leukemia/lymphoma-2 (BCL-2)." (PMID 40108693, 2025). "We characterized melanoma cells and conducted dimensionality reduction clustering, revealing six distinct cell subgroups: C0 TRPM1+ Melanoma cells, C1 PIR+ Melanoma cells, C2 PHLDA2+ Melanoma cells, C3 ID2+ Melanoma cells, C4 PCLAF+ Melanoma cells, and C5 CD74+ Melanoma cells." (PMID 39781353, 2025). "High CD74 and low MIF expression correlated with improved survival outcomes and progression-free survival supporting the idea that the MIF−/CD74+ signature could serve as a prognostic marker in stage III melanoma." (PMID 41159021, 2025). "Cd74/C1q/Aif1-expressing macrophages also are characterized by higher expression of the complement components C1qa and C1qb, which have been positively correlated with immune cell infiltration, apoptosis, and improved survival in previous studies of melanoma." (PMID 41122966, 2025). "CD74 is highly expressed on circulating tumor cells in the majority of melanomas, and its elevated expression in tumor cells may lead to increased levels of the sCD74 soluble form." (PMID 39439891, 2024). "However, most literature on the MIF/CD74 axis in melanoma is limited to cell and animal studies, with few studies reporting on clinical outcomes." (PMID 39028303, 2024). "In addition, CD74’s role in pediatric osteosarcoma, similar to melanoma, involves critical immunological interactions." (PMID 38256356, 2024). "Importantly, CD79a and CD74 have been associated with anti-tumor response in OPSCC and in melanoma patients, respectively." (PMID 38893183, 2024).